IGFBP6 (insulin like growth factor binding protein 6)
Diseases named in the same sentence as IGFBP6 in open-access papers (continued):
Sharing a sentence is not in itself a finding about the gene and the disease.
tumor (continued). "Three novel tumor-derived exosome genes, insulin‐like growth factor binding protein 6 (IGFBP6), VGF (non-acronym), and T-cell Receptor Constant β Chain-1 (TRBC1), which significantly affected the risk score, were also identified." (PMID 36865549, 2023). "RT‐PCR detection of budding RTP gene‐expressions in PDX model post two times 8 Gy irradiation revealed that most RTP gene levels (CST3, CDC37, IGFBP6, ISYNA1, RN7SL2) increased on day 9 when RTP cells were significantly enriched and partial fell back on day 82 when tumor repopulated." (PMID 36658726, 2023). "Comparison of normal and tumor tissue at long-term culture showed increased expression of IGF1R (5-fold, p < 0.0001) and IGFBP6 (3.5-fold, p < 0.01), whereas IGFBP1 (4-fold, p < 0.05), IGFBP3 (2.5-fold, p < 0.01) and IGFBP4 (4-fold, p < 0.01) were downregulated in tumor slices." (PMID 35884847, 2022). "Furthermore, IGFBP-6 expression in CRC tissue is inversely correlated with the survival of patients and connected to the tumor suppressor activity of SEMA3B." (PMID 36013453, 2022). "Thus, IGFBP-6 is related to breast epithelial cell oncogenic activation, directly promoting TME remodeling and increasing tumor invasion." (PMID 35457175, 2022). "Only one report proposed that IGFBP6 acts as a tumor suppressor gene in NPC, and the biological functions of IGFBP6 in NPC progression remain unclear." (PMID 27623076, 2016). "In addition, the RXR-selective agonist (rexinoid)-induced expression of IGFBP6, which occurs following RAR-β-mediated transcriptional activation of RAR/RXR, has been shown to suppress tumor growth." (PMID 23587162, 2013). "Additionally we selected seven other genes, ATF3, ADAMTS1, EGFR, PRNP, IGFBP6, ID4 and FN1, found to be differentially expressed according to tumor subtype and ER+/ER- classification from the tumor-specific differentially expressed gene-set." (PMID 19116033, 2008). "Meanwhile, the protein expression of IGFBP6 was nearly not detected in tumor tissues." (PMID 37950222, 2023). "Our findings support the view that proliferation of chemoresistant tumor cells is controlled within the tumor mass by IGFBP6-producing tumor cells; however, TMZ treatment eliminates this population and enriches the TMZ-resistant cell populationleading to accelerated growth of the entire tumor mass." (PMID 30231881, 2018). "Which cell type is producing IGFBP‐6 to attract tumour cells is not clear yet." (PMID 30117676, 2018). "Downregulation of IGFBP-6 or IGF-I or IGF-II expression levels via siRNAs in breast epithelial cells or knockdown IGF-1R activity on fibroblasts could play an effective role in changing fibroblast mobilization, suppressing TME remodeling and tumor invasion via the IGFs/IGF-1R axis." (PMID 33768092, 2021). "Accordingly, these data place IGFBP-6 within CAF/stromal transcriptional programs and are consistent with (but do not prove) a paracrine contribution to the tumor microenvironment." (PMID 41511360, 2026). "Unlike IGFBP-1 to IGFBP-6, IGFBP-7 inhibits the proliferation of tumor cells by directly binding IGF1R." (PMID 31661774, 2019). "It is likely that a suite of biomarkers, both in the host and tumor will be required rather than single biomarker selection, with some candidates for study in RMS including IGF2, pIGF1R/IGF1R, IGF1, pIRS-1/IRS-1, pIR-A/IR-A, IGFBP-6, and maybe others such as HSPs, PDGFR and Erb2." (PMID 21437217, 2011).
cancer (47 papers, 2005 to 2026). A tumor composed of atypical neoplastic, often pleomorphic cells that invade other tissues. "IGFBP-6 is a context-dependent regulator in the liver—enriched in stellate/cancer-associated fibroblast (CAF) compartments and shaped by lobular zonation—controlling IGF-II availability and exerting IGF-independent actions." (PMID 41511360, 2026). "We found that increased IGFBP6 expression was often associated with better prognosis in these types of cancer." (PMID 35832140, 2022). "We exposed HS5 cells to 200 ng/mL of IGFBP-6 for 24h and 48h and we then analyzed the expression levels of cancer-associated fibroblasts (CAFs) markers." (PMID 34905501, 2021). "The association between IGFBP6 and cancer appears to be more obvious, as a large number of studies on the role of the IGF/IGF1R signaling pathway in oncogenesis have been carried out to date." (PMID 34149804, 2021). "IGFBP-6 has been implicated in human diseases, particularly in cancer biology and fibrosis." (PMID 40723309, 2025). "Interestingly, VIM, besides being a key regulator of cell adhesion and cell–cell interactions, has a well-known role in the EMT process in many types of cancer, while IGFBP6 is particularly implicated in the IGF1-mediated EMT." (PMID 32878319, 2020). "In cancer, IGFBP-6 functions both as a biochemical gatekeeper of IGF-II (via sequestration and PTMs that loosen the trap) and as a stromal organizer within CAF niches that modulate paracrine signaling." (PMID 41511360, 2026). "In conclusion, IGFBP6 exhibits dual functional characteristics in cancer regulation, and its specific mechanism of action remains to be further explored." (PMID 41226409, 2025). "Studies have shown that IGFBP-6 and SHH activators promote mesenchymal stromal cell differentiation while upregulating cancer-associated fibroblast markers." (PMID 40723309, 2025). "Its ability to engage pathways like PI3K/Akt, IGF-1R, and mitochondrial biogenesis links IGFBP-6 to critical outcomes in immune regulation, cancer progression, and fibrotic tissue remodeling." (PMID 40723309, 2025). "By exploring these emerging roles, we aim to elucidate how IGFBP-6 contributes to redox homeostasis and to assess its potential as a therapeutic target in oxidative stress-related diseases, including fibrosis, cancer, and immune dysfunction." (PMID 40723309, 2025). "IGFBP-6 inhibits proliferation in cancer cells which are IGF-2 dependent and can function independently of IGF-2 to inhibit angiogenesis, senescence, and cell migration." (PMID 39698031, 2024). "Knockdown of IGFBP6 was more resistant to apoptosis and increased the proliferation of cancer cells." (PMID 37950222, 2023). "And for the majority of the cancers, IGFBP3, IGFBP4, IGFBP5, IGFBP6 and IGFBP7 were significantly positively associated with stromal, immune as well as ESTIMATE scores including COAD, PCPG, PRAD, READ and STAD." (PMID 37088808, 2023). "IGFBP-6 has cancer-protective properties, plays a role in the immune system and in neuronal protection." (PMID 37253714, 2023). "In this review we have highlighted and described the multiple roles exerted by IGFBP-6 in all these processes, which suggest that it can be considered as a protein of interest also in the cancer development and progression." (PMID 35457175, 2022). "IGFBP-6 also appears to be up-regulated in inflammatory-cancer activated fibroblasts (iCAFs) that are important for maintaining immune suppression and chemoresistance associated with T-cell dysfunction." (PMID 35457175, 2022). "IGFBP6 has been reported as a cancer suppressor that inhibits angiogenesis and induces cancer cell apoptosis." (PMID 36496076, 2022). "Thereafter, we used the PrognoScan database to investigate the prognostic value of IGFBP4 and IGFBP6 expression in patients with different types of cancer." (PMID 35832140, 2022).
cancer (continued). "We also found that both IGFBP-6 and purmorphamine, a SHH activator, were able to induce mesenchymal stromal cells differentiation with an up-regulation of cancer-associated fibroblasts markers." (PMID 34905501, 2021). "It was shown that IGFBP6 acts on different cancer cell lines both by the inhibition of IGFs and by IGF-independent mechanisms in an autocrine and/or paracrine fashion." (PMID 34149804, 2021). "IGFBP-6 expression was examined by immunohistochemical staining, and was visible in the cytoplasm of cancer cells in the organ." (PMID 15846301, 2005). "Additionally, in vivo models of inflammation, fibrosis, and cancer are needed to validate the relevance of IGFBP-6 as a therapeutic target." (PMID 40723309, 2025). "In some cancers, IGFBP-6 promotes proliferation whereas in others it represses proliferation." (PMID 39698031, 2024). "IGFBP6 could also induce expression of various genes related to mitochondrial biogenesis, and then promote cancer cell proliferation, which was controversial with previous studies." (PMID 37950222, 2023). "The expression of IGFBP6 was decreased in almost all cancers except for CHOL, HNSC, and KIRP." (PMID 37199034, 2023). "Furthermore, according to the results from CCLE analysis, IGFBP2, IGFBP3, IGFBP4 and IGFBP6 are highly expressed in most cancer cell lines at the cell level." (PMID 37088808, 2023). "Since Uc.416+A stimulates cell proliferation in culture, it was proposed that low miR-153 expression in GC may contribute to cancer progression by upregulating Uc.416+A which, in turn, decreases IGFBP-6, allowing enhanced IGF-dependent activation of IGF1R." (PMID 35597813, 2022). "On the other hand, the role of both IGFBP2 and IGFBP6 in cancer remains less clearly understood." (PMID 35688943, 2022). "Interestingly, high mRNA level of IGFBP‐6 promotes cancer migration and invasion in an IGF‐independent manner." (PMID 30247804, 2018). "Furthermore, it is increasingly accepted that IGFBP6 is involved in abrogating the proliferation, migration, and survival of cancer cells by inhibiting IGF2." (PMID 30231881, 2018). "Finally, insulin-like growth factor binding protein-6 (IGFBP-6) was shown to inhibit the tumorigenic properties of IGF-II-dependent cancers." (PMID 28977828, 2017). "Gene array studies also showed that IGFBP6 expression has an antiproliferative effect in cancer." (PMID 27623076, 2016). "It was also reported that IGFBP6 promoted cancer cell migration in an IGF-independent manner." (PMID 24920244, 2014). "Overexpression of IGFBP-6 in cancer cells activates programmed cell death." (PMID 21548981, 2011). "Recent evidence suggests Igfbp6 to induce cell migration of cancer cells that could be repressed by inhibitors of p38 and ERK1/2 MAPK signaling." (PMID 21464922, 2011). "Interestingly, abnormal expressions of IGFBP6 and IGFBP7 were associated with cancer." (PMID 36831184, 2023). "PHB2 in the plasma membrane directly contacts insulin-like growth factor binding protein 6 (IGFBP 6) and regulates cancer cell migration by activating MAP kinases, IGF1R (GALNT14/PHB2/IGF1R)." (PMID 38813101, 2024). "IGFBP6 is a relatively specific inhibitor of IGF-II, playing crucial roles in inhibiting cancer cell migration." (PMID 37088808, 2023). "During cancer progression, the TME also changes immune cell infiltration and IGFBP-6 correlates with B cells, CD4+T cells, CD8+T cells, neutrophils, macrophages, and DCs in patients with gastric cancer." (PMID 35457175, 2022). "As already discussed, IGFBP-6 is highly expressed and exerts various actions in fibroblasts, a critical component of the TME during cancer progression." (PMID 35457175, 2022). "Hh pathway is aberrantly activated in cancer with GLI Family Zinc Finger 1, maintaining cell survival by binding the promoter regions and facilitating the transcription of IGFBP-6 and Bcl-2 genes in colorectal carcinomas and pancreatic cancers." (PMID 35457175, 2022).
cancer (continued). "The role of IGFBP‐6 in cancer is complex and stems from its primary role as a modulator of IGF‐II bioavailability and hence as a negative regulator of cancer cell growth." (PMID 30117676, 2018). "IGFBP-6 has a high affinity for binding IGF-2 and is able to inhibit the growth of various cancer cells and activated apoptosis pathways as an IGF-antagonist." (PMID 27464624, 2016). "However, promotion of migration may be pro-tumorigenic, so further studies to determine the mechanisms underlying the differential effects of IGFBP-6 on migration in these cell lines would help in developing an IGFBP-6-based therapeutic for IGF-II-dependent cancers." (PMID 25601855, 2014). "IGFBP6, a specific inhibitor of insulin-like growth factor II (IGF-II), exhibits significantly stronger binding capacity to IGF-II than to IGF-I and can effectively inhibit the proliferation of malignant tumors with high IGF-II expression." (PMID 41226409, 2025). "Meanwhile, similar to other members of the IGFBP family, IGFBP6 can also regulate the activity of cancer cells directly without relying on the IGF signaling pathway." (PMID 41226409, 2025). "While IGFBP-6 has been studied in some cancers it has not been studied extensively in hormone receptor positive breast cancer." (PMID 39698031, 2024). "Among 6 genes that significantly decreased the survival rate of patients, TSD22D3 and IGFBP6 were up-regulated in our results but their expression in STAD patients was lower than in normal tissues, suggesting that CTLs exhibit cytotoxicity partially by down-regulating them in cancer cells." (PMID 38368374, 2024). "In contrast to the ∼5-fold increased IGFBP6 expression in DCs, there was no significant increase after hyperthermia in human aortic endothelial cells (HAEC), human renal cells (HK2), or a number of human cancer cell lines." (PMID 28977828, 2017).
infection (7 papers, 2022 to 2025). The state of being infected such as from the introduction of a foreign agent such as serum, vaccine, antigenic substance or organism. "Moreover, we found that the IGFBP-6 expression was further increased after infection/inflammation stimulation in both the CFBE cell line and HNE cultures." (PMID 36902237, 2023). "Moreover, pre-incubation of F508del-CFTR cell with an anti-IGFBP-6 antibody to abolish its anti-inflammatory activity, increased pro-inflammatory cytokines expression under infection with LPS." (PMID 35903151, 2022). "Therefore, we hypothesized that IGFBP-6 may have an autocrine regulation on CF inflammation by downregulating the pro-inflammatory cytokines to attenuate the airway inflammation under an infection/inflammation condition." (PMID 36902237, 2023). "We then transfected the CFs with si-IGFBP6, followed by infection with or without Lentiviral-Flag-MFAP4 upon TGF-β1 stimulation." (PMID 41208894, 2025). "Moreover, the IGFBP-6 expression was increased in both Wt- and F508del-CFTR CFBE and HNE cells under infection and inflammatory conditions." (PMID 35903151, 2022). "However, the precise role of IGFBP-6 in airway epithelial cells in pathophysiology, in particular in CF under infection/inflammatory conditions is not known." (PMID 35903151, 2022). "However, it is not known whether IGFBP-6 expression is dysregulated in airway epithelial cells under infection/inflammatory conditions." (PMID 35903151, 2022).
cardiovascular disease (2 papers, 2022 to 2025). "In conclusion, while the role of IGFBP-6 in PAH remains largely speculative, its known functions in cardiovascular disease and its potential to regulate fibrosis and inflammation suggest that IGFBP-6 may influence the development of PAH." (PMID 41169887, 2025). "Although direct evidence linking IGFBP-6 to PAH is limited, its established roles in regulating vascular smooth muscle cell behavior and inflammation, as observed in other cardiovascular diseases, indicate it may influence the pathogenesis of PAH through similar mechanisms." (PMID 41169887, 2025).
metabolic disease (2 papers, 2018 to 2025). A congenital disorder (due to inherited enzyme abnormality) or acquired (due to failure of a metabolically important organ) disorder resulting from an abnormal metabolic process. "Although IGFBP6’s roles in metabolic disorders and oncogenesis are documented, its immunoregulatory functions remain sparse." (PMID 40892465, 2025). "At present, the function of IGFBP-6 is not yet clear, but it may be involved in the pathogenesis of metabolic diseases." (PMID 30302116, 2018).
adenocarcinoma (1 paper, 2023). A common cancer characterized by the presence of malignant glandular cells. "The importance of this gene in lung tumors was underlined in a gene expression profile study on lung adenoma vs. adenocarcinoma progression in mice, showing IGFBP-6 as a candidate gene for lung tumor progression, as its downregulation may affect lung tumor progression." (PMID 36902237, 2023). "Thus, in both the adenocarcinoma and squamous cell carcinoma subtypes of NSCLC, the IGFBP-6 expression has been found to be lower compared with healthy tissues, resulting in the decreased function of Semaphorin 3B." (PMID 36902237, 2023).
connective tissue disorder (1 paper, 2024). A disease involving the connective tissue. "For fCEAA, there were many connective tissue disorders (due to the collagen protein family), as well as several proteins linked to miscarriage (COL5A1, IGFBP6, LGALS3); for fEAA, proteins were linked to immunological disorders, primarily due to the chemokine family and their receptors." (PMID 39401228, 2024).
neoplastic disorders (1 paper, 2017). "Since IGFBP6 can exert an inhibitory role on angiogenesis in neoplastic disorders, we cannot rule out that the expression of this protein on microvessels may be due, at least in part, by IGFBP6 activity to limit RA neoangiogenesis." (PMID 28572803, 2017).
neurodevelopmental disorder (1 paper, 2019). A behavioral and cognitive disorder with onset during the developmental period that involves impaired or aberrant development of intellectual, motor, or social functions. "Although the changes were not significant, we observed minor changes in the growth factors, M-SCF, IGFBP-6, IGFBP-2, IGF-2 and PDGF-AA in ZIKV infected astrocytes, which may contribute to ZIKV associated neurodevelopmental disorders." (PMID 30735502, 2019).
IGFBP6 also shares sentences with these, for which no sentence is quoted: cystic fibrosis (2 papers); Hypertension (2); kidney disease (2); non-alcoholic fatty liver disease (2); osteosarcoma (2); sarcoma (2); type 1 diabetes (2); adrenocortical cancer (1); Allergy (1); amyloidosis (1); astrocytoma (1); benign breast disease (1); brain injury (1); breast tumors (1); chronic hepatitis C (1); Chronic Myeloid Leukemia (1); Dupuytren's disease (1); End Stage Renal Disease (1); Fanconi anemia (1); fibromatosis (1); glaucoma (1); glomerulosclerosis (1); Glucose intolerance (1); heart failure (1); Hepatic steatosis (1); IgA nephropathy (1); injury (1); intrahepatic cholangiocarcinoma (1); invasive ductal breast carcinoma (1); ischemic stroke (1).
A further 21 diseases each share a sentence with IGFBP6 in 1 paper.